MIR4436B2 (microRNA 4436b-2)
Synonyms: hsa-mir-4436b-2
Gene: MicroRNA gene on chromosome 2 (110,284,853 to 110,284,943, forward strand). Ensembl gene ENSG00000263881.
Homologues: Paralogues in human: MIR4436B1 (100% identical).